ATRX (ATRX chromatin remodeler)
Diseases named in the same sentence as ATRX in open-access papers (continued):
Sharing a sentence is not in itself a finding about the gene and the disease.
cancer (continued). "Cancers utilizing ALT often have lost functional ATRX, a chromatin remodeling protein, through mutation or deletion, thereby strongly implicating ATRX as an ALT suppressor." (PMID 30226859, 2018). "Cancers with ATRX loss display large, ultrabright telomeric DNA foci that are strongly correlated with the presence of ALT." (PMID 30226859, 2018). "In other words, there must be additional genomic and/or epigenetic events that occur in ALT-positive cancers, cooperating with ATRX loss to allow the ALT mechanism to occur." (PMID 30226859, 2018). "Previous studies have demonstrated that expression of ATRX in an ATRX deficient ALT positive cancer cell can repress ALT phenotypes including the formation of APB." (PMID 30214690, 2018). "Paradoxically, ATRX loss in cancer is beneficial to cell survival through the promotion of the alternative lengthening of telomere (ALT) phenotype." (PMID 27171262, 2016). "Although the mechanisms by which loss of ATRX leads to cancer progression are unclear, we find that all ATRX mutations detected in our study are predicted to be deleterious." (PMID 27590521, 2016). "An overrepresentation of mutated samples in these cancer types was again observed when considering each gene individually (ATRX: p = 0.02; EP400: p < 0.001; NIPBL: p = 0.09; chi-square test)." (PMID 27831464, 2016). "ATRX, a chromatin remodelling factor, is mutated in cancers that maintain telomere length by alternative lengthening of telomeres (ALT)." (PMID 26143912, 2015). "Mutations in the chromatin remodeller ATRX have been identified in many ALT-associated cancers and in a comprehensive study it was found that 90% of ALT-immortalized cell lines lack ATRX24." (PMID 26143912, 2015). "ATRX mutations have also been found in different types of cancer; the tumor suppressor gene is mutated in 90% of cancers that maintain their telomeres by the telomerase-independent “alternative lengthening of telomeres” (ALT) pathway." (PMID 25227228, 2014). "Further complicating a role for ATRX in cell survival is the finding that somatic mutations have been reported in several types of cancer." (PMID 23284920, 2012). "Future studies should investigate whether mutations in ATRX disrupt its interaction with Pds5B and how such changes might contribute to chromosomal instability in cancer." (PMID 40437074, 2025). "Notably, it has been recently reported that cellular ROS are important causative factors in the evolution of ALT-mediated telomere maintenance in ATRX-deficient cancers." (PMID 40750583, 2025). "In addition, ATRX-deficient cancers have been found to be sensitive to chemotherapeutic agents that form TOP1 or poly-ADP ribose polymerase (PARP) DPCs, such as irinotecan or olaparib." (PMID 40748226, 2025). "Another common association in ALT-positive cancer genomes that may be related to T-SCE is mutations in the ATRX/DAXX complex." (PMID 39858038, 2025). "Therefore, in many telomerase-deficient cancers, ATRX inhibits the ALT pathway by promoting cohesion functions in both sister chromatid segregation and telomeric repair of DSBs during G2." (PMID 39479502, 2024). "In the cBioPortal datasets, 884 ATRX mutations have been identified in various cancers." (PMID 39479502, 2024). "Whilst loss of ATRX is a near universal feature of ALT-cancers, it is insufficient in isolation." (PMID 36940725, 2023). "Indeed, we found that neotelomeres were significantly more common in tumors harboring truncating mutations in ATRX than in ATRX-wild-type cancers." (PMID 37945902, 2023).
cancer (continued). "This could suggest that increased ribosome biogenesis as a result of an ATRX nonsense mutation or KO, is a more general phenomenon in cancer." (PMID 37540673, 2023). "Loss of ATRX or its partner DAXX frequently occurs in cancers with the ALT phenotype." (PMID 37754262, 2023). "Almost all ALT+ cancer cells exhibit loss of the ATRX gene and/or its interaction partner DAXX, however, the precise role of ATRX/DAXX loss in the initiation and maintenance of ALT remains unclear." (PMID 36940725, 2023). "Previous studies revealed that ATRX loss is associated with an increase in cancer aggressiveness." (PMID 37231433, 2023). "ATRX loss-of-function mutations are associated with cancers that exhibit the ALT phenotype." (PMID 36245994, 2022). "Thus, the isogenic ATRX KO cells used in this study resemble the ATRX status in most cancer patients with ATRX mutations." (PMID 35406561, 2022). "ATRX is also a bona fide tumor suppressor gene frequently mutated in several cancer types." (PMID 35406561, 2022). "When ATRX function is deficient, chromosomal integrity of cancer cells is at stake." (PMID 36428674, 2022). "Interestingly, as an epigenetic modifier, ATRX has been implicated in cancer and has received a level of attention in the identification of expression modifying drugs." (PMID 36232428, 2022). "Although greater survival benefits from ICIs treatment were observed in female patients with ATRX mutation across various cancer types, these data may over exaggerate the conclusion drawn for GC patients." (PMID 33678158, 2021). "We reasoned that the loss of CTCF binding and global chromatin de-condensation that we observed upon ATRX KO may also explain the inability to form the heterochromatic foci necessary for therapy-induced senescence reported recently in ATRX-deficient cancers." (PMID 34763709, 2021). "Finally, we show that pan-cancer patient samples bearing mutations in either ATRX or ESET had a significantly increased mutation burden at G4-containing DNA." (PMID 34162889, 2021). "The prognostic significance of ATRX mutation on cancer patients varies between researches." (PMID 34729095, 2021). "In other ALT+ cancers, ATRX mutations significantly predominate DAXX mutations." (PMID 34069193, 2021). "Additionally, we discuss the pathogenetic alterations in ALT+ cancers, for example, the mutation status of ATRX and DAXX, and their correlations with the activation of the ALT pathway." (PMID 34069193, 2021). "Subsequently, we attempted to examine whether the sex dipartites in ATRX mutation could be found in other cancer projects from ICGC." (PMID 33678158, 2021). "It should also be noted that somatic mutations in the ATRX gene have been identified in a wide range of cancers that include pancreatic neuroendocrine tumors, gliomas, neuroblastomas, and sarcomas, which will not be discussed here but have been the focus of recent reviews." (PMID 32849845, 2020). "ATRX mutations reached significant enrichment at a cancer cell fraction cutoff of 0.63, which is expected as LOH on the X chromosome occurs infrequently in PANETs and may not always require LOH as a second hit due to X-inactivation." (PMID 32345369, 2020). "Nonetheless, the mechanism underlying the activation of one TMM over another still remains to be clearly elucidated, even if a genetic basis (e.g., TERT promoter mutations, ATRX mutations, telomeric variant repeats) for the activation of either mechanism in cancer is becoming recognized." (PMID 32290440, 2020). "ATRX mutation incidence among human cancers was analyzed from TCGA database." (PMID 33409155, 2020). "Specifically, we asked whether ICP0-null HSV-1, which is unable to effectively infect cells with intact PML NBs, is able to infect and kill ATRX-deficient cancer cells." (PMID 30745338, 2019). "This phenomenon might be further exploited in cancer therapy, for instance by using specific inhibitors of ribosome biogenesis, as recently been shown in ATRX-mutated ALT-positive cancers." (PMID 30556094, 2019).
cancer (continued). "Importantly, high frequency of H3.3 point mutations and/or ATRX/DAXX mutations have been associated with pediatric cancers and with the establishment of a ALT mechanism of telomere maintenance." (PMID 30654820, 2019). "Moreover, a common genetic change in ALT cancers and cell lines is a loss-of-function mutation in ATRX, which is normally a constitutive component of PML NBs." (PMID 30745338, 2019). "The pathogenic consequences of ATRX-dependent genomic instability in the context of cancer are unknown." (PMID 30808951, 2019). "ATRX deficiency is linked to genomic stability in cancer cells." (PMID 30808951, 2019). "Here, we have investigated whether the deficiency of ATRX protein expression that is common in ALT-dependent cancers creates an opportunity for a synthetic-lethal treatment strategy." (PMID 30745338, 2019). "Here, we asked whether ATRX deficiency creates a vulnerability in ALT cancer cells that could be exploited for therapeutic purposes." (PMID 30745338, 2019). "These two cell lines will be valuable tools for the future study of ALT and ATRX loss in cancer." (PMID 30226859, 2018). "Furthermore, cancers that utilize the ALT telomere maintenance mechanism typically display loss of ATRX or, more rarely, DAXX." (PMID 30226859, 2018). "Depletion of the histone chaperone protein ASF1 is able to induce the ALT mechanism concomitant with inhibition of telomerase activity in HeLa cells; moreover (as reported in Section 2.1) mutations in genes encoding for the ATRX/DAXX complex have been found in many ALT cancers." (PMID 29463031, 2018). "It is unclear how these mutations are driving cancer in young patients, but it is likely that ATRX and DAXX deficiencies have adverse effects on chromatin structure that may contribute to the development of cancer." (PMID 29479426, 2018). "The role of H3.3 at heterochromatic regions is unknown, but mutations in the ATRX/Daxx/H3.3 pathway are linked to aberrant telomere lengthening in certain cancers." (PMID 25865896, 2015). "Additionally, multiple reports have demonstrated that ATRX mutation or loss of expression results in ALT and genomic instability, and many ALT cancers harbor mutations in ATRX or DAXX genes encoding proteins that interact with each other at telomeres." (PMID 24810474, 2014). "It has recently been shown that ATRX mutations or the absence of ATRX protein is an almost invariant finding in cell lines exhibiting the ALT phenotype and that various cancers with features consistent with the ALT phenotype are frequently associated with mutations in ATRX, DAXX and/or H3.3." (PMID 24651726, 2014). "In addition, ATRX is amongst the twenty genes most frequently mutated in cancer." (PMID 41688464, 2026). "Given the frequent mutations in ATRX in cancers and its involvement in regulating sister chromatid cohesion and chromosome segregation, our work may have implications for understanding tumorigenesis and for developing therapeutic strategies targeting cohesin dynamics." (PMID 40437074, 2025). "Interestingly, clinical trials in other cancers have also identified that ATRX mutations may be a predictive biomarker of immune checkpoint inhibitor sensitivity." (PMID 39892705, 2025). "Moreover, rDNA copy loss and repeat instability are features of ATRX-mutated cancers." (PMID 32332163, 2020). "Indeed, ATRX loss is associated with an increase in aneuploidy and cancer aggressiveness." (PMID 32376827, 2020).
cancer (continued). "Cancers may also harbor mutations in proteins that are needed for the removal of G-quadruplexes in the genome, such as ATRX, which is mutated in a subset of human cancers that use a non-telomerase mechanism for the elongation of telomeres known as ALT (alternative lengthening of telomeres)." (PMID 31546714, 2019). "The SWI/SNF-like chromatin-remodeling protein ATRX has emerged as a key factor in the regulation of α-globin gene expression, incorporation of histone variants into the chromatin template and, more recently, as a frequently mutated gene across a wide spectrum of cancers." (PMID 24834375, 2014). "A loss of DAXX and/or ATRX expression has been associated with activation of alternative lengthening of telomeres (ALT), a mechanism that enables cancer cells to maintain telomere length and sustain proliferation." (PMID 41472189, 2025). "An analysis of pan-cancer mutational data indicated a preponderance of stop codon mutations in the 5′ end of the SNF2 and helicase chromatin-remodelling domains of ATRX (in particular, R1426*)." (PMID 40468074, 2025). "ATRX is frequently lost in cancer cells utilizing the ALT (alternative lengthening of telomeres) pathway to maintain telomeres, and persistent sister-telomere cohesion has been linked to ATRX loss." (PMID 40437074, 2025). "Alterations in the ATRX/DAXX complex and H3.3 histone have been identified as common mutations amongst ALT-positive cancers." (PMID 39858038, 2025). "ATRX mRNA levels, as depicted in pan-cancer analysis, are significantly upregulated in GBM compared to normal tissues." (PMID 40282990, 2025). "This study aims to investigate alterations in the epithelial nuclear expression levels of DAXX and ATRX in canine carcinomas of the prostate and bladder using immunohistochemical methods combined with AI-assisted digital image analysis." (PMID 41472189, 2025). "Since epithelial nuclear expression was considered more relevant for assessing alterations of DAXX and ATRX in carcinomas, variations in stromal expression and inflammatory cells were not further analysed." (PMID 41472189, 2025). "Gaining insight into ATRX’s role in cancer will help develop more effective and targeted anti-cancer therapies." (PMID 39479502, 2024). "Previous studies have used these genomic alterations as proxies to identify ALT, but depending on histology, as many as 1⁄2 ALT cancers can be wild-type for ATRX or DAXX." (PMID 39224814, 2024). "Lysine demethylase 5C (KDM5C), KDM6A, and ATRX chromatin remodeler (ATRX) are X-escapees that directly regulate epigenetics and play substantial roles in cancer protection." (PMID 38949020, 2024). "In the past decade, high-throughput exon and whole-genome sequencing has shown that mutations in the histone protein ATRX and its partner DAXX are associated with an increased incidence of ALT activation in various cancer types." (PMID 39479502, 2024). "Another member of the SWI/SNF chromatin remodeler group, ATRX, plays an important role in telomere function and cancer which is beginning to be unraveled." (PMID 37754262, 2023). "For the ATRX fusion, gene expression concomitantly was reduced relative to the cancer type supergroup (-3.3 z-score of the fragments per kilobase of transcript per million mapped reads (FPKM) (zfpkm), p < 0.01)." (PMID 37400763, 2023). "In human cancers, ALT activation is intimately linked to the mutational status of the chromatin modulator genes ATRX and DAXX9–13." (PMID 36991019, 2023). "60% of ALT cancers had ATRX structural variations, framework fusions, and single nucleotide mutations." (PMID 36860927, 2023). "In human cancers, ALT activation is strongly associated with mutations of the chromatin modulator genes ATRX and DAXX9–13." (PMID 36991019, 2023). "The precise cause of this TERRA deregulation is not completely understood; however, it has been reported that ALT cancer cells are characterized by reduced compaction of telomeric chromatin as well as ATRX inactivation." (PMID 37046839, 2023).
cancer (continued). "Loss of ATRX and DAXX can also be found in telomerase positive cancers, albeit with low frequency, and some ALT phenotypes have been observed in telomerase-positive cancer lines that have acquired ATRX mutations." (PMID 36805596, 2023). "About 16% of cancers in the Pan-Cancer Analysis of Whole Genomes (PCAWG) dataset were found to harbor somatic mutations in at least one of these three genes (TERT, ATRX, and DAXX) involved in telomere maintenance." (PMID 37761808, 2023). "Taken together, these findings have what we believe to be important implications for precision oncology in ATRX-mutant cancers." (PMID 37200088, 2023). "To model ATRX alterations from human cancer in a primary mouse model, we examined the Cancer Genome Atlas (TCGA), a large next-generation sequencing cancer database." (PMID 37200088, 2023). "In human cancers and immortalized cell lines, ALT activation is closely associated with genetic alterations that affect the histone H3.3 chaperone ATRX-DAXX complex." (PMID 36991019, 2023). "Eventually, seven ATPCR encoding genes, including ATRX, CHD5, CHD7, SMARCA4, SMARCA2, EP400, and ACTB, were identified as driver genes by at least two algorithms in certain cancer types." (PMID 35789070, 2022). "G4-stabilizing drugs have been used for cancer treatment, and they exhibit more toxic effects in BRCA1/2-deficient and ATRX-deficient cancer cells." (PMID 36470428, 2022). "One of the crucial proteins identified in the study was ATRX, a chromatin remodeler frequently mutated in ALT-positive cancer cells." (PMID 35982970, 2022). "Inactivation of ATRX, or, less frequently, its associated protein DAXX, through deleterious mutations, has been increasingly observed in subsets of cancers, and is consistently associated with ALT." (PMID 35740680, 2022). "The discovery that cancer cells rely on ATRX-mediated DNA repair provides a potential therapeutic strategy to sensitize cancer cells to genotoxic chemotherapy and radiotherapy." (PMID 36361605, 2022). "For instance, shared clonal mutations in driver genes such as ATM, ATRX, BRCA1/2, DAXX, MSH3, and MSH6 are associated with aberrations in major cellular signaling pathways like Pathways in cancer, DNA damage response, and regulation of cell cycle." (PMID 36140756, 2022). "As transcriptional factor coregulator involved in cell proliferation and apoptosis, the role of ATRX/DAXX in cancer development is controversial." (PMID 36428674, 2022). "Therefore, we tried to preliminarily explore whether might be sex differences in survival benefits from ATRX mutation through comparing the differences of prognosis outcomes from ATRX mutation between female and male patients across various cancer types in the whole cohort." (PMID 33678158, 2021). "Conversely, ATRX-proficient cancer cells, like HeLa cells, exhibit an uneven contribution from the two subpathways." (PMID 34408777, 2021). "Numerous missense mutations in ATRX have been discovered by whole-exome sequencing of cancers and these reside in the region of ATRX that we have found is able to regulate RNA interactions." (PMID 32376827, 2020). "Mutations in ATRX are associated with Alternative Lengthening of Telomeres (ALT), the process responsible for the maintenance of telomere length in cancer cells thus allowing uncontrolled proliferation." (PMID 31973211, 2020). "This can reveal pathways that are deregulated in cancers with compromised ATRX function that can then be exploited in the development of novel therapies." (PMID 32376827, 2020).